SLFNL1 (schlafen like 1)
Synonyms: FLJ23878
Tractability: No criterion of Open Targets' tractability assessment is met for any kind of drug.
Gene: Protein-coding gene on chromosome 1 (41,015,589 to 41,024,551, reverse strand). Ensembl gene ENSG00000171790.
Subcellular location (Human Protein Atlas): Cytosol
Genetic constraint (gnomAD): Loss-of-function variants: 30 observed, 33.22 expected, observed/expected ratio (o/e) 0.9, 90% interval 0.68 to 1.23. The upper end of that interval is the gene's LOEUF score, 1.23, which puts it in group 5 of 6, group 1 being the genes least tolerant of losing a copy. Missense variants: 553 observed, 528.92 expected, observed/expected ratio (o/e) 1.05, 90% interval 0.97 to 1.12. Synonymous variants: 255 observed, 234.1 expected, observed/expected ratio (o/e) 1.09, 90% interval 0.98 to 1.21.
Homologues: Orthologues: chimpanzee SLFNL1 (99% identical), macaque SLFNL1 (95% identical), mouse Slfnl1 (73% identical), rat Slfnl1 (73% identical), pig SLFNL1 (66% identical), rabbit SLFNL1 (64% identical), dog SLFNL1 (63% identical), guinea pig SLFNL1 (62% identical). Paralogues in human: SLFN11 (20% identical), SLFN14 (19% identical), SLFN13 (18% identical), SLFN5 (15% identical), SLFN12 (13% identical), SLFN12L (13% identical).
Diseases named in the same sentence as SLFNL1 in open-access papers:
SLFNL1 is named in the same sentence as 4 diseases in open-access papers, as found by Europe PMC text mining. Sharing a sentence is not in itself a finding about the gene and the disease. The quoted sentences say what the papers report.
diabetes (1 paper, 2020). "For instance, target genes (FLAD1, SLFNL1, GNS, FBXL18, CYP2B7P) are commonly upregulated genes in metabolic-induced HCC and are associated with risk factors, such as diabetes, obesity, and other metabolic syndromes." (PMID 32228601, 2020).
cancer (1 paper, 2022). A tumor composed of atypical neoplastic, often pleomorphic cells that invade other tissues. "SLFN11, SLFN5, SLFN13, and SLFN12 exhibit a wide range of transcription levels in cancer cells, whereas SLFN12L, SLFN14 and SLFNL1 are barely expressed in cancer cell lines." (PMID 35768579, 2022).
SLFNL1 also shares sentences with these, for which no sentence is quoted: metabolic syndrome (1 paper); Obesity (1).